FOS (Fos proto-oncogene, AP-1 transcription factor subunit)
Diseases named in the same sentence as FOS in open-access papers (continued):
Sharing a sentence is not in itself a finding about the gene and the disease.
heart failure (9 papers, 2020 to 2025). Inability of the heart to pump blood at an adequate rate to meet tissue metabolic requirements. "Second, we identified EGR1, EGR2, FOS and FOSB as potential diagnostic biomarkers and therapeutic targets for heart failure." (PMID 36859608, 2023). "Through PPI network and logistic regression, we identified EGR1, EGR2, FOS and FOSB as potential diagnostic biomarkers and therapeutic targets for heart failure." (PMID 36859608, 2023). "It is reported that FOS is downregulated in cases of heart failure (HF) after MI as well." (PMID 39712244, 2024). "In addition, we identified EGR1, EGR2, FOS and FOSB as potential diagnostic biomarkers and therapeutic targets for heart failure." (PMID 36859608, 2023). "Similar to SysHF HLHS fibroblasts, RVF fibroblasts displayed enriched levels of POSTN, FAP, FOS, and JUN, consistent with a preserved activated fibroblast population observed across human heart failure etiologies." (PMID 40502733, 2025). "FOS and ALOX5 were mainly expressed in macrophages and OGN was mainly expressed in fibroblasts, which were all significantly expressed in disease progression and required more attention to explore the effects on heart failure." (PMID 40060963, 2025). "The screened hub genes, including OGN, FOS and ALOX5, were validated using single-cell sequencing data, cell lines and human samples, which can be therapeutic targets for the treatment to cell senescence under hypoxia and prediction to heart failure progression to HFpEF." (PMID 40060963, 2025).
liver fibrosis (9 papers, 2018 to 2025). "The FOS/IL-17 signaling pathway may be a potential therapeutic target for liver fibrosis, a condition that is considered as an inflammation-mediating process in nonalcoholic steatosis hepatitis." (PMID 33927635, 2021).
non-small cell lung carcinoma (9 papers, 2008 to 2025). A group of at least three distinct histological types of lung cancer, including non-small cell squamous cell carcinoma, adenocarcinoma, and large cell carcinoma. "We have recently demonstrated that aberrant PI3K signalling in Non-Small Cell Lung Cancer cells induces the mRNA expression of oncogenic transcription factors (HMGA1, JUN-B, FOS and MYC)." (PMID 23408974, 2013).
Anorexia (8 papers, 2009 to 2025). Lack of desire to eat (loss of appetite). "FOS is likely to associate with cell differentiation, apoptotic cell death, and depression-related diseases such as bulimia and anorexia." (PMID 22373040, 2011).
Insulin resistance (8 papers, 2011 to 2025). Increased resistance towards insulin, that is, diminished effectiveness of insulin in reducing blood glucose levels. "In obese mouse models, linarin effectively ameliorates insulin resistance and inflammatory responses through modulation of the c-FOS/ARG2 signaling axis." (PMID 40736877, 2025). "The homeostasis model assessment of insulin resistance suggests that FOS supplementation improves insulin sensitivity measured in the fasting state in n-3/- mice, even if it was not statistically significant (p = 0.06)." (PMID 21707971, 2011). "In contrast, four genes such as IL10RA, TLR3, FOS, and PRL demonstrate strong inverse correlations with insulin resistance." (PMID 26089598, 2015). "In contrast, we identified decreased expression of selected genes involved in insulin resistance in adipose tissue, including TLR3, FOS, and PRL, which could induce insulin sensitivity." (PMID 26089598, 2015).
ischemia (8 papers, 2011 to 2024). A hypoperfusion of the BLOOD through an organ or tissue caused by a PATHOLOGIC CONSTRICTION or obstruction of its BLOOD VESSELS, or an absence of BLOOD CIRCULATION. "Numerous investigations (both in vivo and in vitro) have shown that prolonged FOS induction precedes neuronal death following ischemia, and that FOS can facilitate the expression of pro-apoptotic genes resulting in cell death." (PMID 38384585, 2024). "The tissues of cerebral ischemic scars were taken for IHC staining and Western blotting, and the expressions of FOS, DDIT3, DUSP1 and NFIL3 after ischemia were detected." (PMID 38384585, 2024).
ischemic stroke (8 papers, 2017 to 2022). A stroke disorder caused by obstruction of blood flow to the brain, due to thrombotic (local blood clot formation) or embolic (due to a blood clot or other material traveling from another site) event. "Studies on CHRM1 and FOS related to ischemic stroke are very rare, but this just provides new ideas for us to study ischemic stroke." (PMID 34603472, 2021).
itch (8 papers, 2020 to 2025). "In Tac1‐Ai9 mice, quantitative analyses revealed that 16.39% ± 6.78% of Tac1‐positive neurons showed c‐FOS/Tac1 double‐labeling following His‐induced itch, compared to 34.46% ± 5.18% in CQ‐induced acute itch models." (PMID 41204431, 2025). "For chronic itch stimuli, a significant increase in FOS-expressing neurons was also seen in the ZIv (control: 27.83 ± 3.44, AD: 58.67 ± 5.49; P = 0.009), but not in other parts of ZI." (PMID 35299695, 2022). "A combination of PV and FOS immunostaining was firstly performed to test the activation of ZI PV neurons after introduction of acute itch stimuli." (PMID 35299695, 2022).
lymphoma (7 papers, 2012 to 2024). A malignant (clonal) proliferation of B- lymphocytes or T- lymphocytes which involves the lymph nodes, bone marrow and/or extranodal sites. "FOS expression is also repressed by KSHV-encoded miRNA-K12-11 in lymphoma B-cells, illustrating common pathways of virus-induced oncogenesis." (PMID 27123579, 2016). "By applying a combination of various prediction algorithms, we identified the 3′-UTR of c-FOS as a potential target for miR-181a and miR-181b (down-regulated the in EBV-associated lymphomas), CD44 as a potential target of miR-20a and miR-106a, and the IL1R1 as a target of miR-205 and -125a." (PMID 22870299, 2012). "We detected a significant enrichment of c-FOS, FOSL1, FOSL2, c-JUN, and BATF target genes in H3K27ac ChIP–seq peaks upregulated in ITK–SYK+PD-1− lymphoma cells compared to their premalignant ITK–SYK+PD-1+ counterparts." (PMID 37723306, 2023).
Myocardial fibrosis (7 papers, 2022 to 2025). "FOS is a crucial cell proliferation and differentiation regulator that contributes to myocardial fibrosis in post-MI rats, which is the main cause of later deterioration of cardiac function." (PMID 39086489, 2024). "For instance, in cardiac tissue, FOS induces ROS generation and myocardial fibrosis, and inhibiting FOS can significantly reduce inflammation." (PMID 40901474, 2025). "As a target for miR-101A, overexpression of FOS can lead to aggravated myocardial fibrosis after MI, and inhibition of Fos/AP-1 can reduce inflammatory response and cardiac dysfunction." (PMID 39712244, 2024). "It has been shown that inhibition of FOS expression reduces mast cell activation, which could have significant implications for reducing myocardial fibrosis and improving cardiac repair." (PMID 40520937, 2025). "Improved cardiac function and reduced myocardial fibrosis are noted in animals treated with cardiosphere-derived cell-secreted exosomes depending on miR-146a-5p decreases the expression of TRAF6, Smad4, and FOS." (PMID 40492132, 2025).
Salmonella Infections (7 papers, 2016 to 2023). Infections with bacteria of the genus SALMONELLA. "Of these, the FOS gene was simultaneously enriched in the four signaling pathways and although not significantly enriched, these pathways were significantly associated with immunity, including the Toll-like receptor signaling pathway, Salmonella infection, MAPK signaling pathway and apoptosis." (PMID 36557693, 2022). "In the Salmonella infection pathway, FOS is also a downstream mediator of the Rho family GTPases CDC42." (PMID 27474500, 2016).
skin aging (7 papers, 2017 to 2025). The gradual irreversible changes in structure of skin that occur as a result of the passage of time.. "Among aging-related fields, FOS can mediate UV-related skin aging by upregulating matrix metalloproteinases (MMPs) to downregulate TIMP." (PMID 34315853, 2021). "In addition, FOS plays a crucial role in the senescence process of granulosa cells in the ovary, and is responsible for UV-related skin aging." (PMID 37396184, 2023).
cocaine addiction (6 papers, 2018 to 2024). "Proteins closely interacting with FOS protein were also found to participate in other psychoactive drug pathways, such as cocaine addiction and alcoholism." (PMID 30967896, 2019). "Notably, the FOS gene has been identified as a common disease-associated gene shared between progeria syndrome and all five NPDs (MDD, morphine dependence, cocaine dependence, amphetamine abuse, and nicotine dependence)." (PMID 38926475, 2024). "Intriguingly, the FOS gene was found to be common to all five NPDs (MDD, morphine dependence, cocaine dependence, nicotine dependence, and amphetamine dependence) and progeria syndrome." (PMID 38926475, 2024). "Seven nodes including JUN, FOS, RELA, MAPK1, ATF2, HRAS, and CREB1 in the backbone are the recorded genes of alcoholism, amphetamine addiction, or cocaine addiction in the KEGG pathways." (PMID 30899073, 2019). "CTD showed that FOS and EGR1 could be biomarkers of cocaine addiction or play a role in addiction, and EGR1 could be a gene for a therapeutic target in the treatment of cocaine addiction." (PMID 37469839, 2023). "In summary, this study identified four key genes (FOS, IL6, EGR1, and JUN) that might be involved in cocaine addiction mechanisms and had potential roles as biomarkers and therapeutic targets for cocaine addiction." (PMID 37469839, 2023). "Four key genes (JUN, FOS, EGR1, and IL6) were identified and well validated using CTD database correlation analysis, text mining, independent dataset analysis, and enrichment analysis methods, and they might serve as biomarkers of cocaine addiction." (PMID 37469839, 2023).
Hyperglycemia (6 papers, 2021 to 2025). An increased concentration of glucose in the blood. "Transcription factor-based proteins that are activated during hyperglycemia include Jun, FOS, and ATF, which contribute to the synthetization of AP1 dimers, activate multiple stimuli, and regulate various functions." (PMID 38918766, 2024).
malignant glioma (6 papers, 2016 to 2025). A grade III or grade IV glioma arising from the central nervous system. "A possible link has been suggested between c-JUN and c-FOS expression and IL-13Rα2, which is consistent with the expression profile of human IL-13 Rα2 in malignant gliomas." (PMID 36830725, 2023). "FOS was identified as a hypoxia-induced gene in a malignant glioma cell line." (PMID 35874989, 2022). "FOS plays an important role in the radiation resistance mechanism of malignant glioma and may be a potential new target for the treatment of malignant glioma." (PMID 34395252, 2021).
osteoarthritis (6 papers, 2013 to 2024). A noninflammatory degenerative joint disease occurring chiefly in older persons, characterized by degeneration of the articular cartilage, hypertrophy of bone at the margins and changes in the synovial membrane. "Our research suggests that the FOS gene plays a key role in the synovitis of osteoarthritis, and the NRAS gene indirectly acts on FOS, which provides the theoretical basis and ideas for further experimental study." (PMID 29968759, 2018). "In addition, harpagoside also demonstrated its ability to suppress c-FOS functioning as AP-1 transcription factors in osteoarthritis chondrocytes." (PMID 35684573, 2022).
adenoma (5 papers, 2007 to 2025). A neoplasm arising from the epithelium. "A study of 10 g/day short-chain FOS in adenoma and adenoma-free patients resulted in more positive biomarkers in the adenoma-free patients." (PMID 23609775, 2013). "The spatially restricted expression of phosphorylated FOS and JUN in the adrenal cortex adjacent to functional adenomas introduces a novel ancillary criterion, particularly valuable for lesions with equivocal hormone secretion profiles." (PMID 41412035, 2025). "Notably, FOS and JUN activation is restricted to the adrenal cortex adjacent to functional adenomas, highlighting a localized adaptive response to elevated ROS." (PMID 41412035, 2025). "Phosphorylated FOS and JUN were exclusively detected in the adrenal cortex adjacent to functional adenomas (APAs and cortisol-producing adenomas), with negligible levels in cortex adjacent to non-functional adenomas and in normal adrenal cortex." (PMID 41412035, 2025).
astrocytomas (5 papers, 2010 to 2024). "Infection with RVFV induced significant upregulation of ATF3, FOS, KLF4, CXCL10, TNF-α, and PTGS2 in astrocytoma cells at 16 hpi." (PMID 35746681, 2022). "Infection of the astrocytoma cells with EEEV resulted in a significant upregulation of transcription factors ATF3, FOS, and JUN, with both ATF3 and JUN being at least partially transcriptionally dependent on EGR1." (PMID 35746681, 2022). "Genes upregulated in astrocytomas include ID4, CD74 and FOS." (PMID 36865335, 2023).
autism (5 papers, 2018 to 2025). Persistent deficits in social interaction and communication and interaction as well as a markedly restricted repertoire of activity and interest as well as repetitive patterns of behavior. "However, the transcriptional binding-factor motifs implicated in each condition implicated distinct biological mechanisms: neuronal JUN and FOS networks in autism vs. an inflammatory transcriptional network in dup15q microglia." (PMID 39079538, 2024).
Cerebral ischemia (5 papers, 2019 to 2025). Restriction of arterial blood supply to the brain associated with insufficient oxygenation to support the metabolic requirements of the tissue. "The FOS proto-oncogene can be induced in the brain as a result of cerebral ischemia." (PMID 38384585, 2024).
lung fibrosis (5 papers, 2016 to 2025). "Therefore, the differential effects on lung fibrosis between JUN and FOS from this study in fibroblasts and the FOSL2 expression in mice macrophages illustrates the complexity of AP-1 family functions in lung fibrosis." (PMID 34972106, 2021).
nasopharyngeal carcinoma (5 papers, 2009 to 2025). A carcinoma arising from the nasopharyngeal epithelium. "Conversely, reducing FOLR1 levels alters key apoptotic and MAPK pathway genes (BIRC3, caspases, FOS, DUSP1, PRKX, TNFRSF10A), sensitizing taxol-resistant nasopharyngeal carcinoma cells to chemotherapy." (PMID 41439026, 2025).
squamous cell carcinoma (5 papers, 2013 to 2023). A carcinoma arising from squamous epithelial cells. "Preclinical studies indicate that inhibiting SMO can prompt the shift of basal cell carcinoma to squamous cell carcinoma by promoting c-FOS activation of the EGFR/RAS/MAPK pathway." (PMID 38067165, 2023).
chronic kidney disease (4 papers, 2013 to 2025). Impairment of the renal function secondary to chronic kidney damage persisting for three or more months. "Bioinformatic analysis of clinical data from chronic kidney disease (CKD) patients has suggested FOS as a core regulatory gene governing pan-apoptosis in the kidneys of CKD patients." (PMID 41155564, 2025).
coronary heart disease (4 papers, 2015 to 2025). "FOS is implicated in several cellular functions, including those associated with coronary artery disease and endothelial cell migration." (PMID 38674087, 2024). "Understanding the specific mechanisms by which FOS regulates cardiac response to stress can guide targeted therapies for ischemic heart diseases, including MI." (PMID 39069811, 2025). "The involvement of PTP4A1 in endothelial cell migration and coronary artery disease, alongside FOS’s contribution to endothelial cell functions, underscores the significance of these genes in maintaining vascular integrity and function." (PMID 38674087, 2024). "FOS, conversely, contributes to the growth and longevity of cardiomyocytes and intersects with eNOS signaling, while PTP4A1 has a notable role in the development of coronary artery disease." (PMID 38674087, 2024).
disc degeneration (4 papers, 2017 to 2025). "Notably, targeting FOS inhibition may serve as a potential therapeutic strategy to mitigate disc degeneration." (PMID 40901474, 2025).
Hepatitis (4 papers, 2015 to 2023). Inflammation of the liver. "Our statistical analysis showed that high expression of FOS was associated with Hepatitis B Virus (HBV) infection background, alpha-fetoprotein (AFP) level, and macrovascular invasion." (PMID 32280695, 2020).
liver cirrhosis (4 papers, 2017 to 2025). "In the present study, we identify a liver cirrhosis TF—miRNA—mRNA network containing 49 TFs, many of which have been previously implicated in liver disease (e.g. ETS1, FOS, FOXP3, FOXA2, and GATA2)." (PMID 28355233, 2017). "The transcription factor -/lncRNA- microRNA-mRNA network we uncovered that results in immune-mediated liver cirrhosis is comprised of 5 core microRNAs (e.g., miR-203; miR-219-5p), 3 transcription factors (i.e., FOXP3, ETS1 and FOS) and 7 lncRNAs (e.g., ENTS00000671336, ENST00000575137)." (PMID 28355233, 2017). "Notably, HBV-miR-2 activated genes including inflammatory genes like P2RX7 and PYCARD, fibrosis-induced genes like ANXA2 and MIF oncogenic genes like FOS and JUN, which were further verified via RT-qPCR and highly expressed in the particular stages of CHB, liver cirrhosis and HCC." (PMID 40405227, 2025).
postmenopausal osteoporosis (4 papers, 2008 to 2022). Metabolic disorder associated with fractures of the femoral neck, vertebrae, and distal forearm. "In conclusion, the integrative bioinformatics analysis and real-time PCR analysis were utilized to offer fresh light into the role of monocytes in premenopausal osteoporosis and identified FOS, PTPN6, and CTSD as potential biomarkers for postmenopausal osteoporosis." (PMID 35095774, 2021).
prostate tumor (4 papers, 2014 to 2025). "Given the potential tumour suppressor roles of DUSP1, FOS, and ATF3, we compared the expression of these genes in prostate tumours and benign prostate tissue." (PMID 40725480, 2025). "We found low-grade prostate tumours were significantly enriched for the AP-1 family of TF binding sites (JUN, JUNB, JUND and FOS, FOSB and FRA1, and the closely related activating TFs: ATF and CREB), in contrast to high-grade prostate tumours that were enriched for FOXA1, HOXB13 and CDX2." (PMID 34911933, 2021).
psoriasis (4 papers, 2020 to 2023). An autoimmune condition characterized by red, well-delineated plaques with silvery scales that are usually on the extensor surfaces and scalp. "AP-1 transcription factor superfamily (including JUN, JUNB, JUND, FOS, FOSB, FRA1, and FRA2) is essential in the pathogenesis of psoriasis." (PMID 35075118, 2022). "Additional shared signatures between ILCs and T cells were related to genes that regulate tissue residency (FOS and NR4A1; module 18) as well as quiescence (TSC22D3, DUSP1, ZFP36L2, and KLF6; module 22), the latter recently shown to be expressed by plastic skin ILCs in a mouse model of psoriasis." (PMID 37160121, 2023).
sarcoma (4 papers, 2010 to 2018). A usually aggressive malignant neoplasm of the soft tissue or bone. "Secondly, MetacoreTM analysis was performed for remaining 6 genes/miRNAs (FOS, hsa-miR-19a, hsa-miR-22, hsa-miR-24, hsa-miR-215, hsa-miR-302c) where all were found to be related to STS indirectly by their involvement in other mesenchymal tumors/sarcomas except hsa-miR-302c." (PMID 25984907, 2015).